SLC1A5 (solute carrier family 1 member 5)
Diseases named in the same sentence as SLC1A5 in open-access papers (continued):
Sharing a sentence is not in itself a finding about the gene and the disease.
melanoma (continued). "When miR-137 was ectopically expressed in melanoma cells, it was found to bind to SLC1A5 mRNA, inhibiting SLC1A5 glutamine transporter translation." (PMID 32326003, 2020). "Transcript levels of SLC1A5 were uniformly and significantly decreased in all melanoma cell lines in normoxia and hyperoxia, which suggests that glutamine uptake is downregulated by vemurafenib and trametinib irrespective of the oxygen availability." (PMID 31461993, 2019). "In addition, miR-137 inhibits ferroptosis by targeting SLC1A5 in A375 and G-361 melanoma cells in a glutaminolysis-dependent manner, thus inhibiting Gln uptake, while SLC1A5 overexpression can reverse the suppression effect on ferroptosis." (PMID 37065473, 2023). "Different from other cancers, ncRNAs mainly mediate the new system Xc− subunit SLC1A5, which provides us with another dimension of thought concerning ferroptosis regulation and a new perspective on melanoma inhibition and chemotherapy sensitivity through ferroptosis." (PMID 37065473, 2023). "Glutamine transporter SLC1A5 was also proved to be a target for ferroptosis regulation in melanoma." (PMID 36835877, 2023). "Increased SLC1A5 expression has been documented in melanoma, neuroblastoma, and GC." (PMID 34708125, 2021). "Furthermore, targeting SLC1A5 has been shown to sensitize ferroptosis in melanoma." (PMID 36262284, 2022). "Meiying Luo 81 revealed that miR-137 could inhibit glutamine transporter SLC1A5, an inhibitor of ferroptosis, in melanoma cells and that the suppression of SLC1A5 decreased glutamine uptake and MDA accumulation, resulting in ferroptosis and inhibiting the progression of melanoma." (PMID 35342359, 2022). "The SLC1A5 mRNA concentrations were significantly higher in the central nervous system (CNS), breast, colorectum, esophagus, stomach, head and neck, leukemia, lung, lymphoma, melanoma, myeloma, and sarcoma tissues compared with the corresponding normal tissues." (PMID 34367941, 2021). "As SLC1A5-mediated glutamine transport plays a key role in tumor cell metabolism, proliferation, and ferroptosis, blocking SLC1A5 has been shown to successfully prevent tumor cell proliferation in melanoma, non-small-cell lung cancer, prostate cancer and acute myeloid leukemia." (PMID 34568075, 2021). "In melanoma, the expression of glutamine transporters, particularly ASCT2 (SLC1A5), is significantly elevated, facilitating enhanced glutamine uptake." (PMID 40573249, 2025). "In human melanoma cells, when the synthesis of aspartate is inhibited, the GCN2/ATF4 pathway is activated to increase glutamine uptake by upregulating SLC1A5." (PMID 35864117, 2022). "The relevance of glutamine transport in melanoma is supported by data indicating that SLC1A5 and SLC7A11 are overexpressed in melanoma cells when compared to melanocytes." (PMID 31461993, 2019). "During this process, the targeting effect of miR-137 on the glutamine transporter SLC1A5 in the melanoma cells plays a negative role in regulating ferroptosis." (PMID 40019657, 2025). "Furthermore, l‐gamma‐glutamyl‐p‐nitroanilide, an inhibitor of the SLC1A5 (ASCT2) and SLC38A1 (SNAT1) transporters, decreased lipid peroxide levels and rescued erastin‐induced ferroptosis in melanoma cells." (PMID 40703196, 2025). "Furthermore, results of GEPIA analysis showed that ACTB, SLC1A5, VASP, BRBB3, GAS7, ARTN2, and SOX5 were significantly increased in melanoma tissues (p < 0.05)." (PMID 38561355, 2024). "Notably, glioblastoma, melanoma and renal cell carcinoma (RCC) patients with high SLC1A5 expression had a worse prognosis than those with low expression when anti-PD-1 therapy was applied." (PMID 37566748, 2023). "To emphasize the importance of glutamine transporters in melanoma, we investigated the gene expression of glutamine transporters SLC38A1/SNAT1, SLC38A2/SNAT2, SLC1A5/ASCT2, and SLC7A5/LAT1, which showed expression in RNA sequencing analysis in several melanoma cell lines." (PMID 35565278, 2022).
melanoma (continued). "Carrier-mediated proteins overexpressed in melanoma cells include L-type amino acid transporter 1 (LAT1/SLC7A5), L-type amino acid transporter 2 (LAT2/SLC7A8), alanine-serine-cysteine transporter 2 (ASCT2/SLC1A5), and glucose uptake transporter 1 (GLUT1)." (PMID 31717859, 2019). "Mir-137 can inhibit the migration and invasion of melanoma cells 45–47 by targeting various mRNAs such as PIK3R3, TBX3, c-Met, YB1, EZH2, and MITF, and inhibit the proliferation and promote the apoptosis of melanoma cells by competitive binding to genes such as SLC1A5, GLO1, CDK6, etc.." (PMID 33194692, 2020).
lung cancer (48 papers, 2014 to 2025). A malignant neoplasm involving the lung. "In Kaplan-Meier analysis, progressively higher SLC1A5 expression among lung cancer patients was associated with correspondingly lower overall survival rates." (PMID 38904011, 2024). "A study revealed cytoplasmic overexpression of SLC1A5 in lung cancer is associated with cell metabolism, growth, and survival through controlling l-glutamine transportation." (PMID 38705513, 2024). "SLC1A5 plays an important role in glutamine transport by controlling the metabolism, growth, and survival of lung cancer cells, and its variant is a mitochondrial glutamine transporter for cancer metabolic reprogramming." (PMID 34778244, 2021). "This indicates that high expression levels of SLC1A5 might be associated with lung cancer growth in a glutamine-dependent manner." (PMID 36499136, 2022). "Lung cancer cells exhibit a marked dependence on glutamine, facilitated by upregulation of transporters such as alanine, serine, cysteine transporter 2 (ASCT2/SLC1A5) and enhanced glutaminase activity to drive uptake and catabolism." (PMID 41163383, 2025). "Our results suggest that the functional importance of glutamine transport mediated by SLC1A5 in cancer cell proliferation and survival, and SLC1A5 in the glutamine metabolism pathway, is an important therapeutic target for lung cancer." (PMID 38904011, 2024). "Research into several forms of human cancer (e.g., breast, prostate, and lung cancer) has shown that inhibiting the expression of SLC1A5 can reduce glutamine uptake and thereby halt cell proliferation." (PMID 37928274, 2023). "Another study showed that SLC1A5 plays a key role in glutamine transport controlling the growth of lung cancer cells." (PMID 35593463, 2022). "SLC1A5 plays as a vital role in prostate cancer, gastric cancer, lung cancer, and esophageal cancer." (PMID 36273140, 2022). "Previous studies have shown that SLC1A5 plays a key role in glutamine transportation, facilitating the growth and survival of lung cancer cells by regulation of glutamine metabolism." (PMID 36499136, 2022). "In the lung cancer, the driver triad hsa_circ_0051620| SLC1A5–hsa-miR-338-3p—CDH2 and hsa_circ_0066954| POLQ–hsa-miR-338-3p—CDH2 shows the downregulation of the driver gene CDH2, which increases the survival of the patients." (PMID 34055888, 2021). "Recent work has also shown that KEAP1 mutant lung cancer cells are dependent on glutamine and the glutamine transporter ASCT2 (encoded by SLC1A5)." (PMID 33080927, 2020). "The expression of SLC1A4 was reported to be upregulated in breast and lung cancer cell lines, while SLC1A5 was overexpressed in multiple tumor tissues, including lung cancer and breast cancer." (PMID 33269112, 2020). "We found in our list of genes the glutamine transporter SLC1A5 that is important for survival of lung cancer cells." (PMID 25243088, 2014). "Elevated levels of GLS1 and ASCT2 (SLC1A5) were also observed in resistant cells, with overexpression of these proteins linked to a higher mortality risk among lung cancer patients." (PMID 39680480, 2025). "Furthermore, the targeting of SLC1A5 substantially impeded the growth and proliferation of lung cancer cells." (PMID 38317842, 2024). "Our study found that long-term exposure to PM increased SLC1A5 expression in lung cancer." (PMID 38904011, 2024). "It is irrefutable that glutamine uptake also affects chemotherapy sensitivity, as shown by higher levels of SLC1A5 (glutamine transporter) in CR lung cancer cells when compared to wild-type cells and chemoresistance induction upon SLC1A5 overexpression in pancreatic cancer cells." (PMID 38611096, 2024). "Next, we aimed to examine whether the level of SLC1A5 promotes long-term PM exposure to lung cancer cell progression." (PMID 38904011, 2024). "In contrast, TRIM6 silence elevated SLC1A5 expression and ferroptosis of the lung cancer cells." (PMID 36654781, 2023).
lung cancer (continued). "In addition, tumors with high SLC1A5 expression have been found in recent years, including prostate and lung cancer." (PMID 35874898, 2022). "Similarly, in lung cancer, the circRNAs, namely, hsa_circ_0051620| SLC1A5 and hsa_circ_0066954| POLQ, are upregulated and are shown to interact with and regulate driver genes, namely, ADAM17, CDH2, RUNX2, and ZBTB18, through miR-338-3p." (PMID 34055888, 2021). "Moreover, it has been demonstrated that the glutamate-transporter SLC1A5 is essential for cell growth in lung cancer and that the intake of L-glutamine regulates mTOR signalling." (PMID 25415227, 2015). "Also, SLC1A5 mediated glutamine uptake was found to be required for lung cancer cell growth." (PMID 29088718, 2017). "This promotion of SLC1A5 enhances mitochondrial respiration via the glutamine-derived TCA cycle metabolites, consequently stimulating the proliferation of lung cancer cells." (PMID 38904011, 2024). "In lung cancer, Tripartite motif 6 (TRIM6) interacts with SLC1A5 to increase its degradation, thereby promoting ferroptosis and cancer cell death." (PMID 38705513, 2024). "AREG, in turn, upregulates the glutamine transporter SLC1A5 and promotes the accumulation of glutamine-derived TCA cycle metabolites via the EGFR/PI3K/AKT/mTOR signaling pathway, thereby promoting lung cancer cell growth and proliferation." (PMID 38904011, 2024). "SLC1A5 and SLC38A1 are two critical Gln importers and play critical roles in regulating ferroptosis and lung cancer." (PMID 36654781, 2023). "Both TRIM6 and SLC1A5 expressions negatively correlated with patient survival in LUAD database, indicating a clinical role of TRIM6 and SLC1A4 of lung cancer." (PMID 36654781, 2023). "This process is facilitated by the upregulation of the alanine-serine-cysteine transporter 2 (ASCT2, also known as SLC1A5) receptors in different cancer types, including lung cancer." (PMID 35070990, 2021). "Previous studies also indicated that SLC1A5 is upregulated in tumor tissues vs. nontumor tissues in patients with various tumor types, including lung cancer, liver cancer, and colon cancer." (PMID 37566748, 2023). "MiR-338-3p targeting SLC1A5 in retinal pigment epithelium cells and miR-299-3p targeting SLC38A1 in lung cancer cells reduce glutamine absorption and GSH levels to promote ferroptosis, whereas lncOGFRP1 attenuates ferroptosis by blocking miR-299-3p in lung cancer cells." (PMID 37686142, 2023).
prostate carcinoma (47 papers, 2015 to 2025). A carcinoma that arises from epithelial cells of the prostate gland. "Prostate cancer cells regulate glutamine metabolism through ASCT2 (SLC1A5) and LAT1/3 transporters, which support amino acid uptake for proliferation and metastasis." (PMID 41179661, 2025). "ASCT2 (SLC1A5) was shown to correlate with 14C-Fluciclovine uptake in androgen receptor-positive human LNCaP prostate cancer cells in vitro." (PMID 33237350, 2020). "Qian Wang detected that SLC1A5 was up-regulated in prostate cancer patient samples, and promotes prostate cancer proliferation and metastasis in vivo." (PMID 29100325, 2017). "In this study, we demonstrated that the glutamine transporter ASCT2 (SLC1A5) is highly expressed in prostate cancer patient samples." (PMID 25693838, 2015). "Thus, they suggested that targeting SLC1A5 may be a feasible therapeutic approach for prostate cancer." (PMID 29100325, 2017). "ASCT2 (SLC1A5, solute carrier transporters) is a critical transporter responsible for glutamine uptake in prostate cancer cells with its expression is elevated in tumor tissues and further increased in CRPC." (PMID 41179661, 2025). "Pharmacological or genetic inhibition of ASCT2 (SLC1A5) has been shown to reduce the growth of gastric cancer, prostate cancer, and triple-negative breast cancer." (PMID 33511116, 2020). "The protein levels of YAP1, SLC1A5, and GLS1 in benign prostatic hyperplasia (BPH), prostate cancer (PCa) that did not progress to CRPC, and CRPC tissue samples were evaluated using western blotting." (PMID 37773303, 2024).
colorectal cancer (44 papers, 2015 to 2025). A primary or metastatic malignant neoplasm that affects the colon or rectum. "In terms of combination therapy, SLC1A5 was found to be overexpressed in colorectal cancer samples from patients who had developed resistance to cetuximab, an epidermal growth factor receptor inhibitor, and inhibition of SLC1A5 restored cetuximab efficacy." (PMID 40552664, 2025). "In summary, the ATF4/SLC1A5 axis plays a significant role in the progression of colorectal cancer by regulating glutamine metabolism and glycolysis." (PMID 39696988, 2024). "The transcription of SLC7A11, SLC3A2, SLC1A4, and SLC1A5 in colorectal cancer cells were all activated under hypoxia condition." (PMID 39079386, 2024). "Combination of SLC6A14 with SLC1A5 or SLC38A5 had a larger effect in breast versus colorectal cancer cell lines, likely reflecting that tissue of origin can influence SLC substrate selectivity." (PMID 38066114, 2023). "A peptide that specifically targets amino acid transporter SLC1A5 in colorectal cancer cells is identified and conjugated with camptothecin to show selective cytotoxicity to colorectal cancer cells in preclinical models." (PMID 36376440, 2022). "In addition, our previous study reported SLC1A5, an important glutamine transporter, was also upregulated in human colorectal cancer tissues, suggesting extensively activation of the glutamine metabolism pathway." (PMID 27902968, 2017). "Furthermore, expression of glutaminolysis-related genes GLS, SLC7A11 and SLC1A5 were significantly decreased in the colorectal carcinoma cells treated with low-dose PTX." (PMID 28522974, 2017). "In patients with KRAS-mutant human colorectal cancer (CRC), the expression of the transcription factor, YAP1, has been observed to promote the expression of the SLC1A5/ASCT2 gene, which is involved in amino acid uptake." (PMID 40598593, 2025). "Interestingly, a recent study revealed that the lncRNA SYTL5-OT4 could suppress the autophagic degradation of SLC1A5, which accounts for the resistance of colorectal cancer to regorafenib or bevacizumab, expanding the scope of targeting SLC1A5 to antiangiogenic therapy (AAT)." (PMID 39061847, 2024). "The glutamine transporter SLC1A5 (ASCT2), a member of the sodium-dependent ASC transporter family, is overexpressed in gliomas, colorectal carcinoma, hepatocellular carcinoma cells and neuroblastoma." (PMID 37627630, 2023). "Here, we report that the majority of the KRAS mutant colorectal cancer (CRC) cells upregulate selected AATs (SLC7A5/LAT1, SLC38A2/SNAT2, and SLC1A5/ASCT2), which correlates with enhanced uptake of AAs such as glutamine and leucine." (PMID 34003553, 2021). "SLC1A5 and ATF4 expression levels are detected in colorectal cancer tissues." (PMID 39696988, 2024). "SLC1A5, whose ablation sensitized tumors to the mTORC1 inhibitor rapamycin, was also essential for metabolic reprogramming and the rapid proliferation of KRAS-mutant colorectal cancer." (PMID 39061847, 2024). "We also identified other SLC amino acid transporters, such as SLC38A2 and SLC1A5, with the potential to mediate serine transport but they did not seem essential for this process in colorectal cancer cells." (PMID 38066114, 2023). "In this study, we demonstrated that HSF1 could also stimulate glutamine metabolism by regulating the glutamine transporter-SLC1A5/ASCT2, further highlighting the potential of targeting HSF1 in colorectal cancer." (PMID 36010849, 2022). "That involvement was also observed in colorectal cancer cell lines using a synthetic small interfering RNA (siRNA) to attenuate the expression of SLC1A5 and in non-small cell lung cancer (NSCLC) using the l-γ-glutamyl-p-nitroanilide (GPNA) ASCT2 inhibitor." (PMID 33429909, 2021).
colorectal cancer (continued). "By analyzing the mRNA expression of SLC1A5, SLC3A2, and SLC7A5 in human colon cancer samples deposited in The Cancer Genome Atlas (TCGA) database (n = 41 matched pairs of normal and colorectal cancer samples), we found that all three genes had elevated expression in nearly all patients." (PMID 31416966, 2019).